CD4 (CD4 molecule)
Diseases named in the same sentence as CD4 in open-access papers (continued):
Sharing a sentence is not in itself a finding about the gene and the disease.
dermatitis (continued). "Only 15.5% had WHO clinical stage II with either CD4 count below 200 cell/μl, presence of emaciation, dermatosis, persistent cold, prolonged fever, oral thrush, or cutaneous mucosal lesions." (PMID 31971957, 2020). "The most common skin disorders were xerosis (54.8%; mean of CD4 count: 460 cell/mm3) and seborrheic dermatitis (54.4%; mean of CD4 count: 430 cell/mm3)." (PMID 32850174, 2020). "IL-31 is a cytokine produced mainly by activated CD4+ Th2 cells or by mast cells, and is involved in the development of AD-induced skin inflammation and pruritus." (PMID 29910732, 2018). "Antibiotic treatment relieved the dermatitis in Nfkbiz−/− mice, accompanied by decreased numbers of IL-17A- and IL-22-secreting CD4+ T cells." (PMID 28740238, 2017). "Here the authors use mice and human samples to show ARNT-independent DOCK8 inhibition of EPAS1 increases transcription of IL-31 in CD4+ T cells, thus driving skin inflammation." (PMID 28067314, 2017). "In this study, we showed that spontaneous dermatitis developed in Nfkbiz−/− mice along with expansion of IL-17A- and IL-22-secreting CD4+ T cells." (PMID 28740238, 2017). "Here we show a co-existence of typical features of acantholytic dermatosis with low-grade interface dermatitis and perivascular lymphocytic infiltrates composed primarily of CD4+ and CD8+ T-cells." (PMID 27532022, 2016). "In this work, the pathology and molecular biology analyses showed that QP administration inhibited DNFB-induced AD-like dermatitis and infiltration of CD4+ T cells and mast cells on lesions of BALB/c mice." (PMID 24027597, 2013). "Numbers of mast cells were significantly elevated in the dermis of both OVA-sensitized groups, while the increase in macrophages, dermal dendritic cells and CD4+ lymphocytes reached statistical significance only in allergen-induced dermatitis." (PMID 23977003, 2013). "Although less likely, they hypothesized that Desmoglein 3-specific CD4+ T cells induce interphase dermatitis based on data from a mice study." (PMID 40686696, 2025). "This suggested that acquired immune cells, such as CD4-positive T cells, may be less involved in exacerbating dermatitis in the Il18ra−/− model than innate immune cells." (PMID 37964882, 2023). "In that study, TIGIT expression was increased on the AD patients’ CD4+ T cells to impede chronic skin inflammation, and TIGIT expression may be impaired in some AD patients, leading to the deterioration of skin inflammation." (PMID 36993982, 2023). "In this study, immunofluorescence and qPCR analysis showed that MLT significantly reduced the infiltration of CD4+ T cells in rosacea-like dermatitis and suppressed the expression of Th1-related genes (IFN-γ, CCR5, CXCL9, CXCL10) and Th17-related genes (STAT3 and IL-20) in rosacea-like dermatitis." (PMID 34899707, 2021). "As well as highlighting that Hh-mediated transcription in T cells promotes TGF-β signaling to dampen skin inflammation, our RNA-seq of CD4+ T cells from AD skin showed that Hh reduced expression of Ccl24 and Ccl8, and these chemokines recruit eosinophils to the skin." (PMID 31264977, 2019). "The results of specific IgE levels against inhalants and food antigens, cytokine levels, and the CD4/CD8 ratio did not indicate an association of dermatitis with atopy." (PMID 26390923, 2015). "Similarly, the IL-4 producing cells in patients with dermatitis were increased in the CD4+ and CD8+ T cell population among the peripheral blood mononucleocytes." (PMID 19890385, 2009). "Furthermore, we examined whether NGO application can influence the activation of dendritic cells (DCs) and the differentiation of CD4+ T cells into Th1, Th2, and Treg cells during skin inflammation." (PMID 39199350, 2024). "However, the expression levels of GATA3 and ST2 in CD4+ T cells and the numbers of all subsets of inflammatory cells were reduced in Raptor cKO mice, supporting that mTORC1 was essential for the activation of immune cells in skin inflammation induced by MC903." (PMID 36983043, 2023).
dermatitis (continued). "The proliferation of naive CD4+ T cells and Th2 immune response was comparable between Hras+/+ and HrasG12S/+ mice at 7 weeks of age, suggesting that AD-like dermatitis may not be caused by different response of immune cells." (PMID 32792500, 2020). "H&E staining, immunohistochemistry (IHC) staining with CD3, CD4 and CD8 markers were used to evaluate the effects of ORV in in vivo model of skin inflammation using BALB/c mice." (PMID 37376157, 2023). "In DNCB-induced dermatitis mouse model, ORV treatment reduced lesion severity, and skin thickness and numbers of CD3, CD4 and CD8 T cells in the sensitized skin of mice." (PMID 37376157, 2023). "A study has showed that melatonin suppresses the development of AD-like dermatitis in DNFB-treated NC/Nga mice, reduces total serum IgE level, and decreases IL-4 and IFN-γ production by activated CD4+ T cells." (PMID 35163297, 2022). "Although several studies were conducted on skin disorders in HIV-positive patients, the relationship between mucocutaneous lesions and CD4 counts was rarely evaluated." (PMID 32850174, 2020). "The aim of this study is to evaluate the prevalence of skin disorders in HTLV-1-infected individuals and to correlate this prevalence with the initial HTLV-1 proviral load, and initial CD4+ and CD8+T cell count." (PMID 24244779, 2013). "While preventing splenomegaly and reducing histological inflammation, nondepleting anti-CD4 antibody treatment was unable to prevent runting, dermatitis, or premature lethality." (PMID 37156988, 2023). "Our current work recapitulates the anti-inflammatory effect of anti-CD4 antibody treatment on tissue inflammation, although not on dermatitis." (PMID 37156988, 2023). "For example, urolithin A, an ellagitannin metabolite, dose-dependently inhibited (10-50 μM) proliferation and activation of CD4+, by calcium influx impairment through the STIM1/STIM2–Orai1–SOCE pathway, but its effect on dermatitis is still unknown." (PMID 32575730, 2020). "The CD4+ cell count at the onset of HIV infection showed a significant inverse correlation with the viral load at the onset of HIV (r = −0.24, n = 115, p < 0.05) and a significant direct correlation with the interval to the development of HIV-related skin disorders (r = 0.3, n = 115, p < 0.01)." (PMID 40572779, 2025). "In addition, it has also been recently reported that TCM CD8+ and CD4+ T cells from humans express significant levels of non-lymphoid tissue-homing addressins and induce skin inflammation in a mouse model of dermatitis." (PMID 30875408, 2019). "Further, CD4-HBZ mice developed dermatitis not present in the Gzmb-HBZ model." (PMID 29050201, 2017). "CD4/CD8 ratio in workers with dermatitis was not different from that in those without dermatitis." (PMID 26390923, 2015). "Psmb10G209W/+ mice showed defects of both CD4 and CD8 T cells, and Psmb10G209W/G209W mice lacked B as well as T cells and manifested skin disorders with hyperkeratosis and infiltration of neutrophils." (PMID 34819510, 2021). "Various Trm cells, including CD4+ and CD8+, cells can exhibit a high degree of plasticity under steady-state and inflammatory conditions and thus migrate to draining LNs, circulation, distal LNs, and nonspecific skin inflammation sites." (PMID 38779662, 2024). "Therefore, it might be possible that CD4+ T cells expressing AND TCR are continuously, albeit weakly, stimulated with self-peptide/I-Ab complexes in vivo, and induce skin inflammation by producing IL-31 only when DOCK8 expression is lacking." (PMID 28067314, 2017). "Although CD4+ T cells from HBZ-Tg mice and HBZ-Tg/IFN-γ KO mice were similar in their migratory responses to CXCL10, their abilities to infiltrate tissues in vivo may differ, because the HBZ-Tg/IFN-γ KO mice did not develop dermatitis to the same degree that the HBZ-Tg mice did." (PMID 26296091, 2015).
metastatic melanoma (72 papers, 2009 to 2025). A melanoma that has spread from its primary site to another anatomic site. "Data obtained also demonstrate a significant association between low percentages of blood circulating CD4+CD26high T cells and the reduced survival of metastatic melanoma patients with stage III-IV." (PMID 37170241, 2023). "COL3A1, COL5A2 and VEGFA showed dataset-specific correlations; COL3A1 had strong associations with M1 macrophages, while VEGFA was positively correlated with CD4 T cells in metastatic melanomas." (PMID 40943183, 2025). "Utilizing the xCell quantification algorithm, we observed a significant relationship between elevated ZDHHC13 mRNA levels, reduced M2 macrophage infiltration, and increased presence of Memory CD4+ T cells in TCGA human metastatic melanoma samples." (PMID 41321310, 2025). "In our study, using EPIC for immune deconvolution between primary and metastatic melanoma revealed a more heterogenous immune environment, especially in CD4+/CD8+ T cells and macrophages, reflecting varying immune surveillance." (PMID 40722520, 2025). "The CD4+T-cell profile of metastatic melanoma patients was more enriched for inflammatory response, adaptive immunity processes, T-cell activation and lipids’ metabolism." (PMID 40226614, 2025). "Herein, we clearly show, for the first time, that the frequencies of blood circulating CD26high CD4 + T lymphocytes are significantly reduced in metastatic melanoma patients." (PMID 37170241, 2023). "The same paper also reported that higher CTLA-4 protein levels in peripheral CD4+ and CD8+ T cells were associated with a better response to anti-PD1 therapy in metastatic melanoma." (PMID 37197667, 2023). "Our results show that circulating CD4+CD26high T is reduced in metastatic melanoma patients at baseline." (PMID 37170241, 2023). "In terms of the CD4+ T cell subset, peripheral CD4+ T cells are also implicated in mediating antitumor immunity when treated with anti-CTLA-4 antibodies, either from mouse models or patients with metastatic melanoma." (PMID 35504878, 2022). "Using a mouse model of metastatic melanoma, we found that transferring tumor-specific CD4+ T cells into recipients induces substantial regression of the established metastatic tumors." (PMID 35784297, 2022). "Immunogenic tumors often contain a mixture of reactive CD8 and CD4 T-cell clones, and neoantigen reactive CD4 T cells were common in metastatic melanoma." (PMID 34201655, 2021). "One study reports on a patient with metastatic melanoma who received autologous NY-ESO-1 directed CD4+ cloned T cells and experienced a durable clinical response." (PMID 33546283, 2021). "Moving to potential future biomarkers, increased frequency of expression of TIM‐3 and CXCR6+ on CD4+ T cells in metastatic melanoma patients with PD was confirmed." (PMID 34129290, 2021). "A similar kinetic process is identified in CD8+ and CD4+ T cells collected from a patient with metastatic melanoma." (PMID 29360859, 2018). "For example, a case study demonstrated that treatment with HLA-DP4-restricted NY-ESO-1 transduced CD4+ T cells can induce complete regression of a refractory metastatic melanoma, with a durable response ongoing at 22 months." (PMID 29770138, 2018). "It is also expressed at higher levels on T cell subsets in patients with metastatic melanoma, including CD4+ and CD8+ cells and Tregs." (PMID 26633468, 2015). "Recently, the clinical relevance of adoptively transferred tumor antigen-specific CD4+ T cells was impressively documented in a report describing the complete remission of stage IV metastatic melanoma." (PMID 21152437, 2010). "Lastly, we observed elevated numbers of infiltrating CD4+ CTLs in pre-anti-PD-1 treatment biopsies of metastatic melanoma patients, suggesting that CD4 T-cells may contribute actively to an anti-tumor response." (PMID 40897819, 2025).
metastatic melanoma (continued). "A possible explanation for the transient change in peripheral blood CD4 + T cell frequencies is that atezolizumab treatment leads to early mobilization of T helper cells into lymph node tissues (the site of the metastatic melanoma); however, this requires further investigation." (PMID 38365756, 2024). "To address whether Nivolumab may affect the immune perturbations observed in metastatic melanoma patients, we compared the frequency of CD4+CD26+ T cells at W0 with those obtained after 12 weeks (W1) of treatment in a sub-cohort of 33 patients." (PMID 37170241, 2023). "We found that B cell memory, CD4+ T cell (resting and activated), M1 Macrophage and Myeloid dendritic cell showed different abundances of infiltration through the process taking place in highly metastatic melanoma." (PMID 37762054, 2023). "Therefore, our study aimed to investigate for the first time the frequency of circulating CD4+ T cells with varying levels of CD26 by flow cytometry in metastatic melanoma patients treated with nivolumab compared to healthy subjects." (PMID 37170241, 2023). "The blockade of PD-L1 signaling resulted in an expansion of tumor specific CD4+ T cells, which could better control the established metastatic melanoma." (PMID 35784297, 2022). "Because CD4+ TEM expansion is principally a feature of metastatic melanoma, we next asked whether CD4+ TEM% was somehow associated with tumour burden." (PMID 33664251, 2021). "Accordingly, a decrease in peripheral blood Tregs after ipilimumab treatment in metastatic melanoma patients was associated to disease control and OS, while the baseline percentage of CD25+ FoxP3+ CD4 T cells in NSCLC patients treated with nivolumab was higher in non-responders." (PMID 32244396, 2020). "In the same report, they demonstrated that higher numbers of CD8+ TIL but not CD4+ TIL were associated with increased survival in metastatic melanomas." (PMID 33013886, 2020). "According to the identification of specific CD4 T cell subsets, a study including 46 metastatic melanoma patients treated with nivolumab showed that increase in Th9 frequency in responders, which also correlated with higher levels of serum TGFβ and higher percentages of IL4-producing CD4 T cells." (PMID 32244396, 2020). "Thus, absolute numbers of circulating CD4+ T cells and B cells are altered in patients with metastatic melanoma." (PMID 29546435, 2018). "In addition, our findings suggest premature contraction of the CD4+ TNaive cell compartment in young patients with metastatic melanoma." (PMID 29546435, 2018). "CD4-depleted animals showed a strong reduction in the number of lung nodules compared to non-depleted animals, showing that CD4+ T cells are important for metastatic melanoma development." (PMID 29899823, 2018). "In addition, NY-ESO-1-specific CD4+ T cells isolated from a metastatic melanoma patient after treatment with ipilimumab were able to directly lyse autologous cancer cells, suggesting an added clinical benefit of eliciting a NY-ESO-1 CD4+ cellular response." (PMID 29770138, 2018). "Interestingly, we also found that the defect in STAT1 activation in CD4+ T cells and NK cell subsets in the patients with metastatic melanoma was age-related, while normal donors had a stable response with age." (PMID 27153543, 2016). "Interestingly, an increasing CD4+/CD8+ ratio has previously been postulated as a predicator of positive outcome in patients with metastatic melanoma receiving chemo-immunotherapy (combination cytotoxic chemotherapy plus IFN)." (PMID 26633468, 2015). "This transgenic mouse was recently developed in our laboratory using the HLA-A2 restricted high-affinity TCR reactive to human tyrosinase-derived peptide, YMDGTMSQV, isolated from class I-restricted CD4+ T cells from tumor infiltrating lymphocytes of a patient with metastatic melanoma." (PMID 24586745, 2014).
metastatic melanoma (continued). "Interestingly, the application of autologous CD4+ T cells have also shown to induce prolonged clinical remission in metastatic melanoma patients." (PMID 23071696, 2012). "In addition to classic helper function, CD4+ T cells also have cytolytic activity depending on class II-restricted recognition of tumor antigens, and have exhibited anti-tumor effects in patients with metastatic melanoma." (PMID 26527725, 2016). "Interestingly, studies in patients with metastatic melanoma have revealed overwhelming Th2-driven chronic inflammation, suggesting that the elimination of CD4 T cells could relieve major barriers to the generation of CD8 T cell immunity in these patients." (PMID 22046294, 2011). "In parallel, activated CD4+memory T-cell abundance in the peripheral blood and TCR diversity at baseline were recognized as predictors of irAEs in metastatic melanoma patients." (PMID 40226614, 2025). "Interleukin (IL)-2 was approved by the FDA in 1998 for metastatic melanoma therapy and can act directly on effector CD8+ T and regulatory CD4+ T cells." (PMID 34400883, 2021). "We found that, indeed, C36L1 significantly increased the levels of CD4+ T cells from 6.86 to 13.35%, CD8+ cytotoxic T cells from 6.11 to 17.6%, and NK1.1+ natural killer (NK) cells from 8.44 to 16.13%, in lung metastatic melanoma." (PMID 29875777, 2018). "In fact, in metastatic melanomas, BMAL1 expression exhibited a strong positive correlation with the expression of dendritic cell markers, T-cell markers CD4 and CD8A, and T-cell activation/differentiation markers." (PMID 29946530, 2018). "This is consistent with a previous report showing up-regulation of GPR160 in cancerous prostate duct cells, CD4+CD56+ hematodermic neoplasm, metastatic melanoma and nasopharyngeal carcinoma cells." (PMID 26871479, 2016). "Interleukin-2 (IL-2), a protein produced primarily by CD4+ T-cells that activates and induces proliferation of natural killer (NK) cells, CD8+, and CD4+ T cells, is FDA-approved for the treatment of metastatic melanoma." (PMID 24743024, 2014). "We next evaluated the mean percentage of CD4+ and CD8+ T cells expressing ILT2 and found it to be significantly elevated in metastatic melanoma patients compared to healthy donors (n = 11 and 10-11, respectively; P = 0.002 and P = 0.0009, respectively)." (PMID 24829758, 2014). "In a separate trial (NCT01159288), exosomes derived from autologous dendritic cells (DEX) were used as a therapeutic vaccine for patients with metastatic melanoma, indicating safety and tolerability, yet lacking strong responses from CD4+ or CD8+ T cells." (PMID 41142789, 2025). "In this regard, in a study of patients with irresectable and/or metastatic melanoma (MM) (n = 43) and NSCLC (n = 40) treated with nivolumab, tumors with increased inflammatory gene transcripts had increased ratios of CD4+ and CD8+ Tcm cells to Teff in the blood." (PMID 39273452, 2024). "To confirm these results, we analyzed a publicly available CyTOF dataset and found that CTLA-4 protein levels were reduced in circulating immune cells (CD45+), CD4+ T cells, and Treg cells (CD4+CD25+CD127-) in metastatic melanoma patients compared to healthy donors." (PMID 37197667, 2023). "ITGAL can promote an increase in the ratio of CD4 and CD8 T cells, improving the survival rate of patients with metastatic melanoma, which may explain why high expression of ITGAL is associated with a better prognosis." (PMID 37388230, 2023). "Altogether, these results are intriguing as the baseline levels of CD4 + T cells, expressing high levels of CD26, may be a predictive marker for treatment response to nivolumab in metastatic melanoma patients." (PMID 37170241, 2023). "Interestingly, nPKC-θ expression was also low in CD4+ human Jurkat T cells and CD8+ T cells isolated from immunotherapy responders with metastatic melanoma." (PMID 35326747, 2022).